AKT3 (AKT serine/threonine kinase 3)
Diseases named in the same sentence as AKT3 in open-access papers (continued):
Sharing a sentence is not in itself a finding about the gene and the disease.
tumor (continued). "AKT2 and AKT3 also have pro‐tumour functions but whether HSF1 can be regulated by these isoforms remains unknown." (PMID 35080342, 2022). "In addition, shRNA knockdown of AKT3 inhibited triple negative breast cancer cell spheroid growth and tumour formation in in vivo xenograft studies." (PMID 35406381, 2022). "In addition, circ_AKT3, PTPN14 and P-gp levels were reduced and miR-206 abundance was increased in tumor samples from sh-circ_AKT3 group in comparison to sh-NC group." (PMID 35233464, 2022). "In contrast, ablation of AKT3 has been shown to be associated with no major effect on the tumor growth but significantly decreases the tumorigenic potential of triple-negative breast cancer cells." (PMID 35892586, 2022). "Moreover, in the phase I study, M2698 was shown to strongly inhibit AKT1, AKT3, and p70S6K in the tumor tissue." (PMID 35525984, 2022). "It is speculated that decreased AKT3 expression improves cell dedifferentiation and tumor progression." (PMID 34209611, 2021). "In addition, the mRNA and protein expression of AKT3 was reduced, and the miR-532-3p expression was elevated in tumor tissues of mice treated with si-circNRIP1, and oe-circNRIP1 treatment led to opposite results." (PMID 34660257, 2021). "In this study we identify a previously unknown role for PPARG in up-regulating AKT3, which promotes PGC1α localisation to the nucleus and consequently increases mitochondrial mass and function, increasing ATP levels, tumour growth and metastasis." (PMID 33654198, 2021). "Moreover, miR-29b acts to target Akt3 and inhibit angiogenesis and tumor growth by acting as an anti-angiogenesis and anti-tumorigenesis agent through the VEGF and C-myc arrest in BC cells." (PMID 34778378, 2021). "High AKT3 expression in the tumour epithelial compartment may thus be used as a surrogate marker for EMT and may allow for a selection of CRC patients that could benefit from AKT3-targeted therapy." (PMID 33673003, 2021). "The decrease in AKT3 gene transcription suggests its action as a tumor suppressor." (PMID 34209611, 2021). "Surprisingly data from RNA-Seq of the tumour samples identified AKT3 as a novel target of PPARG and the probable link between PPARG and the observed changes at the mitochondrial level given the known role of AKT3 in PGC1a regulation and mitochondrial biogenesis." (PMID 33654198, 2021). "When PPARG expression from in vivo experiments is compared, it does in fact appear that OE19 tumours have significantly higher PPARG expression than NTS tumours, which could account for the elevated AKT3 levels observed in OE19 tumours." (PMID 33654198, 2021). "In contrast, Toulany and colleagues showed that knockdown of Akt1 and to some extent Akt3, but not Akt2, inhibited cell proliferation and tumor growth in K-Ras-mutated MDA-MB-231 cells." (PMID 34298660, 2021). "Finally, the cancer cell selective expression of AKT3 in tumour resection material was confirmed using RNAscope analysis on tissue slides and on TMA cores available for the AMC90 patient dataset." (PMID 33673003, 2021). "In TGCT, the TR4/AKT3 signaling was identified as a potential promotor of tumor metastasis." (PMID 34882061, 2021). "Our results suggest that CAFs that express AKT3 induce tumor infiltration by other TAM phenotypes." (PMID 33799788, 2021). "Co-treatment with cisplatin in mice carrying xenografts formed from knockdown of AKT2 (4T1 shAKT2) and AKT3 (4T1 shAKT3) in 4T1 cells dramatically attenuated tumor formation in mice after two weeks as compared with that of mice with knockdown of AKT1 (4T1 shAKT1) treated with cisplatin." (PMID 33227065, 2020).
tumor (continued). "Further, the Patient 1 tumor, its derivative cell lines and UW-CSCC2 all harbored copy number amplifications in genes of the PI3K/mTOR signaling pathway, as well as mutations in AKT3, supporting this as a key targetable pathway in metastatic cSCC." (PMID 33333825, 2020). "Furthermore, the levels of Akt3 and p27, in xenograft tumor excised from nude mice, were explored by Western blot analysis." (PMID 32633726, 2020). "The tumor suppressive role of AKT3-174aa was validated in vitro and in vivo." (PMID 31470874, 2019). "Furthermore, PI3K/Akt signaling and especially Akt through its isoforms Akt1 and Akt3—has been shown to play a regulatory role in the DNA damage response of tumor cells through the NHEJ and potentially HR repair mechanisms." (PMID 31847370, 2019). "Next, we tested the tumor-suppressive role of AKT3-174aa in mice intracanal tumor models." (PMID 31470874, 2019). "Conversely, knocking down AKT3-174aa promoted the tumor formation of SW1783 and Hs683 cells in vivo, and the wild-type SW1783 and Hs683 cells could not do the same." (PMID 31470874, 2019). "Meanwhile, the mRNA level of AKT3 was dramatically elevated in tumor tissue (n = 30)." (PMID 31582906, 2019). "Although the tumor-suppressive role of AKT3-174aa prevents its druggable potential, we think that the low expression of AKT3-174aa may allow for AKT be easily exposed to p-PDK1 or SETDB1 in GBM, and this makes AKT more sensitive to activation cascades." (PMID 31470874, 2019). "The role of AKT3 in proliferation, apoptosis and tumor growth was examined next." (PMID 31752925, 2019). "The authors could link differences in polarity and hydropathy values of the pleckstrin homology domain and the regulatory domain between the Akt isoforms to the tumor-promoting effects of Akt2 and Akt3." (PMID 29562639, 2018). "At present, the specific role of Akt3 in tumours is not fully understood." (PMID 29518912, 2018). "In addition, we identify AKT3 as a potential central marker of tumor malignancy, as its levels in BT are slightly lower than in NE, and significantly further decreased in MT compared to BT." (PMID 29321820, 2017). "Because mutations in the PI3K/Akt pathway located in AKT1, AKT2, AKT3, PTEN, and PIK3CA were analyzed altogether, their results did not provide any direct insights on the association between PIK3CA mutation status and primary tumor location." (PMID 29207615, 2017). "Finally, we showed that AKT isoforms 1, 2 and 3 are differentially upregulated in primary human HCCs and that overexpression of AKT correlates with worse tumor biology and pathologic features (AKT3) and prognosis (AKT1)." (PMID 27611696, 2016). "However, GFAP levels were dramatically decreased in the tumor cells from c-Myc/kRas/Akt3 combination mice." (PMID 26993778, 2016). "The Akt family comprises three members (Akt1, Akt2, and Akt3) that share significant overall homological and kinase domain similarities but diverge in the linker region and the PH domain; they play distinct roles in development and tumor formation." (PMID 26993778, 2016). "Moreover, HCC tumors with a poor prognostic cluster A (p<0.0001), hepatic stem cell (HS) subtype (p<0.01), higher tumor grade (p<0.03), vascular invasion (p<0.05) and metastasis (p<0.01) had significantly greater expression of AKT3." (PMID 27611696, 2016). "On the other hand, recent data indicates that AKT3 inhibits cancer cell migration, which may therefore influence the metastatic potential of tumor cells." (PMID 26741489, 2016). "The locus on chromosome 13 associated with total AKT3 levels (tsQTL11) shared the same marker peak as tQTL3, related to tumor latency, lifespan and tumor incidence, suggesting that the effect of tQTL3 could occur through the regulation of total AKT3 levels." (PMID 25853295, 2015). "Elevation of AKT3 significantly promoted tumor growth of PC-3 xenografts in nude mice." (PMID 26318033, 2015).
tumor (continued). "Immunohistochemical staining of lung tissue sections from AJEJJenv infected WT, Akt1−/−, Akt2−/−, and Akt3−/− mice with a Jenv-specific monoclonal antibody revealed that all tumors uniformly express the viral oncogene suggesting that tumor initiation in this model was dependent on Jenv expression." (PMID 24722238, 2014). "All Akt3−/− mice exhibited multiple focal lesions at 12 and 20 weeks post-infection and by 32 weeks mice showed signs of respiratory distress due to excessive tumor burden." (PMID 24722238, 2014). "Among the three human isoforms Akt1, Akt2, and Akt3, it has been suggested that Akt1 may have an important role in tumor initiation and tumor growth." (PMID 18184439, 2008). "Indeed, while the inhibition of Akt1 was significantly linked to the reduced proliferation and tumor progression of in vivo OC cells, the silencing of Akt2 increased the tumor growth, and Akt3-KO mice displayed an intermediate phenotype, leaning towards the stimulation of OC cell growth." (PMID 38929705, 2024). "This could perharps modulate AKT3 then further stimulate the signalling for tumour to progress." (PMID 37476187, 2023). "Also, we found that AKT3 expression levels in tumor tissues were higher than in normal ones." (PMID 34882061, 2021). "However, whether AKT3-derived circRNAs also enhanced chemo-resistance and promoted deterioration of neoplasms (e.g. TNBC) remained ambiguous." (PMID 33495420, 2021). "Moreover, it has been shown that the increased AKT3 gene expression could promote tumor malignancy and resistance to DNA-damaging chemotherapy compounds through activation of DNA repair pathway in glioma tumor cells." (PMID 34127725, 2021). "Previous studies demonstrated that AKT3 could promote tumor development in different human cancers." (PMID 34103010, 2021). "Additionally, AKT3 was reported to exert a tumor suppressive function in GBM." (PMID 31470874, 2019). "Viewed in the context of the results of our earlier studies, these data suggest that the tumor phenotype may be due to the promotion of FGF-2 responsiveness by the Akt3/IWS1 pathway and the induction of EMT and stem cell self-renewal by FGF-2 via the FGF-2/KDM2B/miR-101/EZH2 pathway." (PMID 28515962, 2017). "In addition, AKT3 downregulations might contribute to tumor growth, metastasis, and cell migration in HGSOC." (PMID 29321820, 2017). "Finally, we see a slight compensatory increase in Akt1 expression in the uninfected and tumor bearing Akt2−/− and Akt3−/− mice, which could contribute to the accelerated tumor development in these mice." (PMID 24722238, 2014). "For instance, miR-145 has been suggested by several studies to act as a tumor suppressor in TC by inhibiting various pathways, including RAB5C, PI3K/AKT3, and protein kinase B." (PMID 39928612, 2025). "Compared to the control group, the tumor group exhibited higher positive expression of AIFM1, AKT3, and IL1RAP." (PMID 40324259, 2025). "Akt3 depletion resulted in impaired CAF immunosuppressive activity, potentially counteracting tumor progression, and intratumor infiltration of Akt3 positive CAFs correlated to unfavorable prognosis among HNSCC patients." (PMID 38279300, 2024). "Specifically, AKT2 exhibited significant overexpression in tumor tissue (p = 0.01), while AKT2, AKT3, PPARG, and PTEN displayed significant increases in normal tissue (p ≤ 0.04)." (PMID 38505269, 2024). "It has been reported that the promoter methylation levels of AKT3, CD147, LINE1, MAGEA1, RASSF1A, and SFRP1 were considerably correlated with OS, tumor volume, and cancer properties." (PMID 38206300, 2024). "Six key genes were located within malignant tumor cells and enriched predominantly in the cytoplasm of tumor cells, including PERP, BAK1, VDAC1, FOXO3, AKT3, and IGF1." (PMID 36900213, 2023). "MiR-16 is dysregulated in OSCC, and it functions as a tumor suppressor miRNA, thus inhibiting cell proliferation and inducing apoptosis in OSCC by decreasing AKT3." (PMID 37998329, 2023).
tumor (continued). "By binding the 3′-UTR of AKT3 and controlling AKT3 gene expression, miR-122 inhibits HCC cell proliferation, increases the chemosensitivity of HCC cells, and attenuates HCC tumor growth in vivo." (PMID 37998329, 2023). "Based on AKT1/AKT2 and AKT1/AKT3 ratios, we define four AKT classes which were related to patients’ survival, tumor morphology and BRCA1 expression." (PMID 35053468, 2022). "In contrast, ectopic expression of PD-L1 can eliminate the tumor suppressive effect of downregulation of EMX2OS and AKT3 or overexpression of miR-654 in OC cells." (PMID 34496886, 2021). "Similar to these published reports, in this study, we too observed that NSCLC patient tumor tissues were positive for PI3K, AKT3, p-AKT3, mTOR, and p-mTOR proteins by IHC." (PMID 33833996, 2021). "By analyzing a CLIP‐Seq dataset reported in a previous study, we found that some mRNAs among the top 100 IGF2BP2‐binding mRNAs, such as C‐MYC, AKT3, IGF1R, and CCND2, were closely related to tumor progression." (PMID 34185427, 2021). "Built on this assumption, circRNAs produced from AKT3, an oncogene in melanoma, hepatocellular carcinoma [PMID: 25370363] and TNBC, were also likely to be responsible for tumor progression, including TNBC." (PMID 33495420, 2021). "Further validation of PPARG’s effect on this pathway was established through immunoblot of tumour lysates probing for PPARG, AKT3, PGC1α, CRM1 and VDAC1." (PMID 33654198, 2021). "Intriguingly, the differential expression of AKT3 was unique as its two closely related AKT family members, AKT1 and AKT2, were found to be similarly expressed across all CMSs in cell lines and tumours." (PMID 33673003, 2021). "We found that all AKT3 transcripts were methylated to varying degrees, and the level was significantly lower in TGCT tumor tissues compared to controls." (PMID 34882061, 2021). "Our results establish that AKT3 is expressed in the epithelial, cancer cell compartment of CMS4 CRC in human tumours and in various preclinical models, ranging from PDX models to cell lines, representing this particular subtype." (PMID 33673003, 2021). "Therefore, AKT3 might play an important role in TGCT anti-tumor immunity." (PMID 34882061, 2021). "There are three subtypes of AKT, namely AKT1, AKT2, and AKT3, among which AKT2 is responsible for tumor progression and metastasis through regulating EMT-related proteins." (PMID 33123457, 2020). "Therefore, while ATP-competitive inhibitors might be useful in cases where AKT3 is constitutively activated and acts as an oncogenic driver, allosteric AKT3-sparing compounds might be preferable in tumours where AKT3 has been shown to have growth inhibitory properties." (PMID 32453400, 2020). "miR-424-5p, which was reported to affect growth through inhibiting Akt3 and E2F348, was down-regulated in tumor tissues and its expression levels in HCC tissues correlated with tumor size, multiple nodules, tumor stage and overall survival outcome." (PMID 31320713, 2019). "In the present study, we found that down-regulated miR-145 and up-regulated AKT3 are observed in ESCC tissues and cells, implying that miR-145 is tumor suppressor in ESCC." (PMID 31582906, 2019). "There was increased expression in the HCC tumor compared to the benign adjacent tissue in the following proportions of HCCs: AKT1 (48.2%), AKT2 (29.1%) and AKT3 (70.0%)." (PMID 27611696, 2016). "We also conducted IHC experiments of AKT2, AKT3, PKM2 and HK2 levels in xenograft tumor tissue sections." (PMID 26512921, 2015). "Moreover, AKT3 phosphorylates the NADPH oxidase subunit p47phox, significantly increasing reactive oxygen species (ROS) levels, which triggers DDR and inhibits tumor cell proliferation." (PMID 40725100, 2025).
tumor (continued). "The phytochemical selectively upregulated tumor suppressor miRNAs, including miR-16-5p, miR-34a-5p, and miR-200a-5p in PC3 and LNCaP cells, suggesting potential involvement of pathways such as AKT3, TGF-β, and BRD4-mediated androgen receptor signaling in its mechanism of action." (PMID 41465187, 2025). "To determine whether AKT3 or FGFR2 can serve as potential targets, we first constructed the F0 generation PDX tumor models with biospecimens from PPLELC patients and transplanted into F1 generation PDXs for efficacy experiments." (PMID 40057671, 2025). "AKT3-174aa competes with phosphorylated PDK1 (pyruvate dehydrogenase kinase 1), blocks AKT-thr308 phosphorylation, regulates PI3K/AKT signaling, and inhibits GBM cell proliferation, radiation resistance, and anti-tumor activity in vivo." (PMID 40034125, 2025). "Furthermore, the AKT3 and FGFR2 overexpression is significantly correlated with the late clinical stage, large tumor size, increased lymph node metastasis and poor prognosis." (PMID 40057671, 2025). "Specifically, MYC showed positive correlations with oncogenic factors HDAC2, HDAC3, AKT2, and AKT3, while demonstrating negative correlations with tumor suppressors PTEN and FOXO1." (PMID 40229260, 2025). "However, only one gene, AKT2, presented a significant increase in tumor tissue (p = 0.01), and four genes showed a significant increase in normal tissue (AKT2, AKT3, PPARG, and PTEN; p ≤ 0.04)." (PMID 38505269, 2024). "Here, we demonstrate that oncogenic K-Ras(V12) regulates tumor cell migration by activating the phosphatidylinositol 3-kinases (PI3-K)/Akt pathway and induces the expression of E-cadherin and neural cell adhesion molecule (NCAM) by upregulation of Akt3." (PMID 38291468, 2024). "Interestingly, we found that while the AKT2 and AKT3 KO WM1799 cells developed tumors similarly to NT cells, only the AKT1 KO cells had significantly delayed tumor growth." (PMID 37894325, 2023). "Intriguingly, we identified copy number alterations (CNAs) of various oncogenes and tumor suppressors (e.g. Yap1, Braf, Foxo1, Akt3 and Rb1) in RMS tumors developing in DK mice, which might play important roles for tumor formation and growth." (PMID 36376321, 2022). "The results of this integrative cBioPortal analysis suggest that genes AKT3, CHUK and PTEN behave like tumor suppressors, while AKT1, AKT2, EGFR, and PIK3AP1 show oncogenic behavior and are involved in enhanced activity of the EGFR-PI3K-AKT-mTOR signaling pathway." (PMID 34209611, 2021). "Nevertheless, despite a higher tumor burden in bone, inoculation of 231-BO cells lacking AKT3 did not significantly promote osteolysis." (PMID 33670586, 2021). "We revealed an absent increase in osteolysis in the AKT3 knockdown of 231-BO cells despite the about 3-fold higher tumor burden." (PMID 33670586, 2021). "Here, we demonstrated a significantly negative correlation of AKT3 expression with the abundance of tumor-infiltrating cells, including activated CD8 + T cells, CD8+ memory T cells, activated dendritic cells, and monocytes." (PMID 34882061, 2021). "AKT3 might participate in TGCT progression through multiple signaling pathways, such as ErbB, oxidative phosphorylation, and affecting tumor immune infiltration." (PMID 34882061, 2021). "This analysis is however strongly confounded by the fact that high expression of AKT3 is not a sole reflection of tumours that have activated an EMT programme but contains tumours rich in stromal fibroblasts expressing AKT3 as well." (PMID 33673003, 2021). "In this present study, we found that depletion of Akt2 or Akt3 did not alter the tumor development or local invasion while we confirmed our prior data with the Akt1 knock out model." (PMID 33110146, 2020). "Akt3 is known to induce VEGF secretion and angiogenesis in tumor." (PMID 32746845, 2020).